IL6 (interleukin 6)
Diseases named in the same sentence as IL6 in open-access papers (continued):
Sharing a sentence is not in itself a finding about the gene and the disease.
breast tumor (continued). "Together, these data suggest that elevated EphA2 expression in breast tumor cells promotes osteolytic disease in bone metastasis, at least in part, by upregulating IL‐6, which in turn enhances osteoclast differentiation to facilitate osteolysis." (PMID 33869989, 2021). "During tumoroid transformation to a tumor in a host tissue, high expression of certain cytokines such as IL-6 and IL-8 regulates the immune and inflammatory responses and enhances the breast tumor growth." (PMID 34821729, 2021). "In the tumor microenvironment, stromal cells and cancer cells act as the major source of IL-6, and the expression of IL-6 is increased in breast tumors." (PMID 34944905, 2021). "Our study showed consistent results, the IL-6 level was significantly higher in the plasma and breast tumor tissues of the Fvb mice, and IL-6 also impaired the maturation of the BMDCs in the Fvb mice in vitro." (PMID 33568170, 2021). "It was also reported that IL-6 produced by mature adipocytes and fibroblast supports breast tumor growth and metastasis." (PMID 33171330, 2021). "What's more, the expression level of IL-6 was also decreased in the breast tumor tissues of the Fvb.B6 mice than in the Fvb mice." (PMID 33568170, 2021). "Recently we showed that interleukin-6 (IL-6) induced DNA hypomethylation of VEGFR2 promoter in endothelial cells isolated from clinically characterized human breast tumors and facilitated disordered angiogenesis in 3D spheroid models." (PMID 34613483, 2021). "Another study demonstrated that leukemia inhibitory factor receptor (LIFR), whose ligand is a member of the interleukin-6 (IL-6) family of cytokines, confers a dormant phenotype of disseminated breast tumor cells." (PMID 34064392, 2021). "Another study demonstrated that mice which drank milk fermented with Lactobacillus helveticus R389 had elevated levels of IL-10 and decreased IL-6 levels, both in serum and mammary cells, leading to breast tumour inhibition." (PMID 34201776, 2021). "For example, TNFα and/or IL-6 were strongly connected to endocrine resistance in luminal-A breast tumors, in patients as well as in model systems of cultured cells or mice." (PMID 33585241, 2020). "The inhibition of RCC2 expression significantly decreased breast tumor growth and IL-6 levels in the tumor-bearing mice." (PMID 32565805, 2020). "Cooperativity of CCL5 with IL-6 was also noted when CM of MSCs promoted breast tumor cell migration." (PMID 32582148, 2020). "Further assessment revealed that the breast tumor expression of OSM correlated with the expression of IL-6, with a Spearman coefficient of 0.576 (p < 0.0001)." (PMID 31007849, 2019). "The study presents a crucial interaction by which EMT is regulated by IL-6 in response to fractionated radiation in breast tumors, where Notch-2 upregulation is frequently accompanied a by IL-6-dependent STAT3 activation." (PMID 31766724, 2019). "IL-6, in particular, has been demonstrated to promote breast tumor cell proliferation and metastatic capacity and to decrease patient survival." (PMID 31007849, 2019). "Here, we utilize MDSCs generated from BMDCs in vitro with GM-CSF and IL-6 (referred to as BM-MDSCs) to visualize their recruitment and fate after adoptive transfer in breast tumor-bearing mice using optical imaging (OI)." (PMID 29677215, 2018). "Our current results are in accordance with previously published studies and indicate that IL-6/IL-6R mediated signaling is a critical therapeutic target for inhibiting early stage breast tumor progression." (PMID 30134951, 2018). "In our study, notably, blocking IL-6 signaling with intravenous injections of IL-6 neutralizing antibodies suppressed xenograft tumor growth, suggesting that IL-6 signaling would be therapeutic target for inhibiting early stage breast tumor progression." (PMID 30134951, 2018).
breast tumor (continued). "Comparatively little is known, however, about the roles of the macrophage-associated cytokines Interleukin-6 (IL-6) and interleukin-10 (IL-10) in the regulation of LVI, and LN metastasis or even their expression in breast tumours." (PMID 29256156, 2018). "Antibodies of IL-6 would significantly inhibit the pro-metastasis effect of adipocytes when co-cultured with breast tumor cells." (PMID 30013512, 2018). "In this study, we showed that SNAIL1 regulates expression of cytokines in primary breast tumor cells including IL-1α, IL-6, TNFα, and GM-CSF." (PMID 29593211, 2018). "The mRNA expression of IL-6 was upregulated by 3-fold in breast tumor cells when co-cultured with adipocytes, whereas both IL-1β and TNFα were not obviously affected." (PMID 30013512, 2018). "In this study, we show that BM-MDSCs generated in vitro using BMDCs treated with IL-6 and GM-CSF, show similar morphological and functional properties to G-MDSCs from breast tumor-bearing mice." (PMID 29677215, 2018). "Dual immunostaining of breast tumor and lymph node (from progressive metastatic patient) sections for Shh (green) and IL-6 (red) revealed that both Shh and IL-6 were found within the same epithelial and fibroblast cell compartment." (PMID 28496132, 2017). "Both early operable (n = 45) and progressive metastatic (n = 65) breast tumors exhibited strong IL-6 signals that disappeared either after surgery and/or chemotherapy, ﻿respectively, verifying the tumors as the source." (PMID 28496132, 2017). "Promotion of CS/IC self-renewal and mammosphere growth of human breast tumors, including triple negative breast cancers (TNBC), has been further associated with IL-6, IL-8 and TGF-β." (PMID 28768501, 2017). "Within the breast tumor, the highest levels of IL-6 are found on the tumor edge, in stromal/immune cells and areas of lymphovascular invasion." (PMID 28416734, 2017). "In comparison to matched normal breast tissue, breast tumors produce significantly increased levels of IL-6, and these levels also increase proportionately with higher tumor grade." (PMID 29088874, 2017). "In summary, our data suggests that only breast tumors in which the activation of STAT3 is dependent on IL-6 will be sensitive to therapies against this cytokine." (PMID 27602583, 2016). "A major source of IL-6 in breast tumors are naturally occurring senescent cells; inhibition of IL-6 from this source impairs the growth of a PDX." (PMID 27602583, 2016). "Non-canonical Notch signaling has recently been shown to influence the IL-6/JAK/STAT pathway in breast tumors in a fashion that requires NF-κB." (PMID 24611064, 2014). "Depletion of IL-6 from s-UCMSCs conditioned medium partially abrogated the stimulatory effect of s-UCMSCs on the proliferation and migration of breast tumor cells." (PMID 25419563, 2014). "Infiltration of these tumor-promoting immune cells as well as various inflammatory cytokines, particularly TNF-α and IL-6, has been found in the breast tumor microenvironment." (PMID 23372803, 2013). "A delayed breast tumor growth was also demonstrated for milk fermented with L. helveticus R389 due to decreasing interleukin-6 (IL-6) and increasing IL-10 in serum, mammary glands, and tumor-infiltrating immune cells." (PMID 23335916, 2012). "IL-6 contributes to the induction of skin tumors, triggers malignant features in breast tumor mammospheres, and participates in suppression of antigen-specific anti-tumor immunity through up-regulation of macrophage B7-H4 expression." (PMID 20544025, 2010). "A large body of reports demonstrated the stimulatory role for TNF-α, IL-1 and IL-6 in the proliferation of breast tumors." (PMID 21209958, 2010). "64pT is a syngeneic breast tumour cell, highly expressing Mage-b and highly secreting IL-6 (3000 pg ml−1)." (PMID 18728665, 2008). "In contrast, breast tumours exhibited high levels of IL-6, G-CSF and IFN-γ, and extremely high levels of IL-8, MCP-1 and MIP-1β." (PMID 17261184, 2007).
breast tumor (continued). "We examined IL-6 levels in primary breast tumors and found a positive correlation between pStat3 and IL-6 expression." (PMID 17531096, 2007). "Janus kinase inhibitors and monoclonal anti-IL6 receptor antibodies significantly decrease ALDH expression, colony, and mammosphere formation, suggesting possible use of pharmacological inhibitors of the IL-6/JAK2/STAT3 pathway in breast tumors with elevated POU1F1 levels." (PMID 41857068, 2026). "IL-1β and IL-6 expression is increased in the early stages of breast malignancies and is positively correlated with advanced tumor stages, indicating a critical role in breast tumor metastasis." (PMID 40035822, 2025). "Indeed, Th17 cells are found in greater numbers within breast tumors, and another inducer of Th17 responses, IL-6, is elevated in various cancers, and plays a central role in the systemic inflammation associated with cachexia." (PMID 39389979, 2024). "Pro-inflammatory mediators such as TNF-α and IL-6 are key players in cancer-related inflammation, and inhibition of these cytokines could protect against chemically induced breast tumors." (PMID 38818375, 2024). "Exposure of rat- and human-derived adipose tissue to γ-radiation produces a significant inflammatory response, and inflammatory cytokines secreted by breast tumors, including IL-1β, IL-6, IL-10, and TNF-α, stimulate ATX secretion by activating the NF-κB pathway." (PMID 36880535, 2023). "Additionally, ER-positive breast tumor cells were described to produce lower levels of IL-6 than ER-negative breast tumor cells." (PMID 37340387, 2023). "It remains to be determined whether IL-6 targeting drugs are more effective against breast tumors of women of AA compared to women of EA." (PMID 37709737, 2023). "A positive correlation between phosphorylated STAT3 (pSTAT3) and IL-6 expression in primary breast tumors was first reported by Berishaj and collaborators, who also demonstrated that in vitro blockade of gp130 or IL-6 sequestration led to a decrease of pSTAT3 levels." (PMID 35163731, 2022). "IL-6-induced signaling in breast tumors mainly triggers STAT3 activation." (PMID 35163731, 2022). "Due to the direct action of lower exosomal let-7s upon increased CXCLs, IL-6, and IL-10 secretion in BALFs, we believe that the conversion of N2 neutrophils also occurs in the pre-metastatic lung in patients with breast tumor with lower exosomal let-7s." (PMID 35173168, 2022). "Interestingly, an IL6 activation signature revealed that pathway activity as measured in breast tumour samples correlated with circulating serum IL6 levels." (PMID 34834425, 2021). "The YHD inhibition of 4T1 breast tumor growth may be related to the negative regulation of the JAK/STAT3 pathway by repressing the expression of IL-6 and TGF-β (Mao, Feng & Gong, 2018)." (PMID 32461838, 2020). "However, breast tumors are heterogeneous where pockets of both M1 macrophages and proinflammatory cytokines (TNFα, IL-12, and IL-6) as well as M2 macrophages and anti-inflammatory cytokines exist." (PMID 33414685, 2020). "IL1B, IL6, TNF, IL8 and CXCR4 mRNA levels were significantly increased in the high AHR-expressing ERα-negative breast tumor subpopulation, while these associations were only observed for IL6 and CSF1 in the ERα-positive tumor subgroup." (PMID 29320557, 2018). "The IL-6/JAK/STAT3 feedback loop has been well documented in breast tumor growth and metastasis." (PMID 29934528, 2018). "On one hand, YHD inhibited the growth of 4T1 breast tumors via decreasing the number of MDSCs in the tumor microenvironment and through specific mechanisms associated with the downregulation of the expression of iNOS, ARG-1, IL-6, TGF-β, and p-STAT3." (PMID 30581487, 2018). "Moreover, Stat3 is responsible for mediating the effect of IL-6 on CSC maintenance in human breast tumor cells." (PMID 30004423, 2018).
breast tumor (continued). "For instance, the cytokine Oncostatin M, belonging to the Interleukin-6 (IL-6) family of cytokines, enhances HIF-1α protein stability and induces HIF-1α de novo synthesis via activation of mTORC2 in breast Tumor Associated macrophages (TAMs), leading to inflammatory reprograming." (PMID 29996493, 2018). "Moreover, the stimulatory effect of adipose stromal cells on migration and invasion of breast tumor cells is abrogated by a depletion of IL-6." (PMID 29389973, 2018). "Additionally, IL-6 is a key molecule in the dynamic equilibrium between CSCs and non cancer stem cells (NCSCs) via IL-6 secretion, and IL-6 can convert NCSCs to CSCs in breast and prostate cell lines as well as from cells derived from human breast tumors." (PMID 27732936, 2016). "Our results indicate that only a fraction of breast tumors are responsive to anti-IL-6 therapies." (PMID 27602583, 2016). "In addition, studies have shown that treatment of breast tumor xenografts with neutralizing antibodies to CCL2 lead to increased expression of IL-6 and VEGF when anti-CCL2 treatment was interrupted." (PMID 27283985, 2016). "The current review will focus on the impact of IL-6 and in the breast tumor microenvironment." (PMID 25881039, 2015). "Moreover, the data also delineate molecular association of resistin and IL-6 at the regulatory level and establish STAT3 as a vital mediator in conferring the phenotypic response of resistin in breast tumor cells." (PMID 25868978, 2015). "and IL-6, are present in the microenvironment of most malignant tissues, including breast tumors." (PMID 24457902, 2014). "Much of the IL-6 and IL-6sR available to stimulate breast tumour aromatase activity may originate from infiltrating macrophages and lymphocytes." (PMID 12592380, 2003). "As previously observed, IL-6+IL-6sR markedly stimulated aromatase activity (7.7–20.8-fold) in fibroblasts derived from reduction mammoplasty tissue, tissue proximal to tumours and breast tumours." (PMID 12592380, 2003). "Using short-term epithelial cultures established from primary breast tumours, we have examined whether IL-6 could directly affect transcriptional activity of oestrogen reception α (ERα)." (PMID 10755407, 2000). "In addition, A-FABP expression in CD11b+F4/80+MHCII-Ly6C- phenotype TAMs facilitates protumor IL-6/STAT3 signaling by regulating the NFkB/miR-29b pathway, and A-FABP deficiency significantly decreases the growth and spread of breast tumors in transgenic and syngeneic tumor models." (PMID 36880535, 2023). "Hence, the data depicts that TAMs express high levels of IL-6 in breast tumors." (PMID 35300689, 2022). "Interestingly, the expression levels of PTGS2 (-4.80-fold change) and EGFR (-2.45-fold change) regulated by hsa-mirR128, ABCB1 (-2.21-fold change), IGF1 (-2.19-fold change), and IL6 (-2.85-fold change) regulated by hsa-miR-223, were significantly reduced in breast tumour tissue." (PMID 32577155, 2020). "Notably, increased expression levels of IL-6 and p-STAT3 have been detected at the leading edge of breast tumors and linked to advanced disease, suggesting a mechanistic role of the JAK/STAT cascade in promoting breast tumor progression." (PMID 29934528, 2018). "However, autocrine factors may also contribute to cancer cell homing, similar to the release of IL-6 and IL-8 from breast tumors that draws circulating tumor cells back to the primary tumor site." (PMID 23730620, 2013). "There is now good evidence that malignant fibroblasts produce IL-6 and IL-6sR and that tumour infiltrating macrophages and lymphocytes may also be an important source of factors that can stimulate oestrogen synthesis in breast tumours." (PMID 12592380, 2003). "The upregulated IL-6 expression promotes EMT through the JAK/STAT3 signaling pathway, thereby suppresses E-Cadherin expression, and facilitates breast tumor cell migration and invasion." (PMID 40821783, 2025).
breast tumor (continued). "For example, ADSC-secreted interleukin-6 (IL-6) can induce epithelial–mesenchymal transition (EMT) and promote invasion in both normal and primary breast tumor epithelial cells." (PMID 40019720, 2025). "Breast tumors infiltrated by MMP-11+ mononuclear inflammatory cells are more likely to metastasize, have high levels of interleukin (IL)-1, IL-5, IL-6, IL-17, interferon (IFN), and NFB, and an increased CD68+/(CD3+CD20+) cell ratio at the invasive front." (PMID 39190284, 2024). "Pro-inflammatory mediators (IL-6, CCL2, COX2, and TNF-α) are generally up-regulated in breast tumor stroma; IL-1, IL-6, IL-8, IL-11, IL-18 and IL-23 are among the most studied inflammatory factors involved in inflammation, TNBC, invasion and metastasis." (PMID 36834660, 2023). "On the other hand, the stimulation of macrophages to secrete pro-inflammatory factors such as IL-1b, IL-6, and TNF-α by exosomal transfer of miR-183 led to tumor growth and metastasis of the 4T1 breast tumor model in vivo." (PMID 36012638, 2022). "Histological analysis of human breast tumors has shown that the adipocytes present at their invasive front also expressed high levels of MMP-11 and IL-6, in contrast to adipocytes from healthy tissues where these proteins are absent." (PMID 35268073, 2022). "A significantly increased expression of IL-6, IL-8, TGF-β1, and TNF-α in SC and CC isolated from primary breast tumors having a high percentage of BCSCs; further supports the significant role of inflammatory tumor environment in the expansion of CSCs." (PMID 34778599, 2021). "RCC2 expression upregulated IL-6, IGF1, and TWIST1 expression both in animal models and in cultured ER + breast tumor cells." (PMID 32565805, 2020). "We found that IL6, IL8, and CCL7 are expressed at significant levels in the normal breast, ER+ breast tumors, and the matching tumor-adjacent breast tissue." (PMID 31419632, 2019). "Recent data have shown that the JAK2/STAT3 pathway is preferentially activated in CD44 + CD24- breast CSCs through the excessive production of IL6 and promotes CSC growth in breast tumors." (PMID 31511084, 2019). "Further analysis revealed IL-6, CCL2, and MMP9 were upregulated in breast tumors with low compared to high IGF-1R." (PMID 30458886, 2018). "In co-culture condition, although both IL-6 and TNF-α mRNA level in adipocytes were significantly upregulated in the presence of breast tumor cells, the level of TNF-α was undetectable in the supernatant of adipocytes with or without breast tumor cells." (PMID 30013512, 2018). "Expression levels of multiple cytokines were higher in ER- compared to ER+ breast tumors, including IFN-γ, TNF-α, and IL-6 and IL-8." (PMID 28899409, 2017). "MCP-1 and IL6 decreased and VEGF level increased in all types of breast tumors with low TGFBR2 expression." (PMID 25280532, 2014). "In particular, interleukin-6 (IL-6) and tumor necrosis factor-alpha (TNF-α) have been reported to be elevated in the blood serum of patients diagnosed with advanced stage breast tumor and correlate with an increased number and size of metastatic sites." (PMID 23372803, 2013). "These structures release pro-inflammatory factors, including interleukins (IL-6, IL-8), monocyte chemotactic protein (MCP-1), and tumor necrosis factor alpha (TNFα), which promote a pro-inflammatory environment in the breast tumor microenvironment, thereby facilitating the development of BC." (PMID 40165893, 2025). "Oral administration of BBR for 5 wk led to a trend but a nonsignificant reduction in the proinflammatory cytokine IL-6 levels in the breast tumor tissue of the BBR-treated group compared with the control group (P > 0.05)." (PMID 39896297, 2025). "Targeting IL-6 signaling pathways may disrupt CSC function and sensitize breast tumors to conventional therapies, potentially improving patient outcomes." (PMID 39896297, 2025).